CXCL12 (C-X-C motif chemokine ligand 12)
Diseases named in the same sentence as CXCL12 in open-access papers (continued):
Sharing a sentence is not in itself a finding about the gene and the disease.
cancer (continued). "In particular, we show that the anti-cancer action triggered by metformin relies on its ability to inhibit the insulin/IR-mediated transduction pathway as well as the insulin-generated feedforward loop that couples CXCL12 induction by CAFs to CXCR4 expression by BCAHC‐1 cells." (PMID 35672854, 2022). "Furthermore, the use of inhibitors targeting the oncogenic CXCL12 axis in combination with current immunotherapies should be considered and may provide hope for improving cancer treatments." (PMID 35406582, 2022). "Thus, the ability of cancer cells to coat themselves with CXCL12 may contribute to resistance to immunotherapy." (PMID 35046049, 2022). "Additionally, the increased expression of c-miR-126 in response to exercise could alter the TME and inhibit cancer cell invasion and metastasis by suppressing the expression of stromal cell-derived factor-1 alpha (CXCL12) and chemokine ligand 2 (CCL2)." (PMID 35454797, 2022). "Moreover, CXCL12 activating CXCR4 promotes the transfer of proto-cancer mitochondria between cells." (PMID 35630915, 2022). "Moreover, the CXCL12/CXCR4/7 axis could also facilitate cancer cells proliferation and survival through ERK, AKT, and Ras signaling pathways." (PMID 36612163, 2022). "CXCL12 could promote cancer progression and is a potent chemoattractant for haematopoietic cells." (PMID 35894174, 2022). "Furthermore, its critical role in shaping CXCL12 gradients suggests that ACKR3 inhibition could have major effects on both cancer and immune cell trafficking." (PMID 35159113, 2022). "Overall, the emerging scenario suggests that the relative expression levels of CXCR4 and ACKR3 and whether they are expressed in the same or distinct subpopulations of cancer or stromal cells, may have an impact on CXCL12-mediated responses, highlighting a relevant question for future research." (PMID 36233192, 2022). "With this concern in mind, and considering the fact that CXCR4 is a major receptor of CXCL12, we further tested whether artificial overexpression of ligand CXCL12 in macrophages can prevent the resensitization of cancer cells to docetaxel in the presence of pexidartinib." (PMID 34069563, 2021). "Additionally, TPBG modulates cell adhesion, cytoskeletal organization, and mobility by facilitating functional C-X-C chemokine receptor type 4 (CXCR4) expression, leading to C-X-C motif chemokine 12 (CXCL12)-mediated chemotaxis in differentiating ES cells, embryonic fibroblasts, and cancer cells." (PMID 34876581, 2021). "Furthermore, the CXCL12/CXCR4 axis is involved in cancer cell intravasation." (PMID 33530455, 2021). "However, the inhibitory effect of AMD3100 on CXCR4 significantly suppressed CXCL12 signaling-mediated recruitment of immune cells in HBV liver, and significantly disrupted the effect of CXCL12 on the self-renewal capacity of HBx-expressing cancer stem-like cells (CSCs) in HBV-related HCC." (PMID 34386499, 2021). "The difference in cell growth induced by BoxA and CXCL12 is critical from a translational point of view: Even if both were equally potent in inducing Immunogenic Surrender, injecting CXCL12 would also promote cancer growth, while our data indicate that injecting BoxA does restrain it." (PMID 33956406, 2021). "Importantly, multiple studies have reported that CXCL12/CXCR-4 axis activation enhances cancer cell adhesion, migration, and invasion, leading to increased metastasis, and specific blockage via neutralizing antibodies targeting CXCR4 can partly interrupt this process." (PMID 34069563, 2021). "In addition, our model describes the kinetic parameters of fibroblast signaling molecules (SLIT2 and CXCL12) with a polynomial which is dependent on cancer cell signaling factors (LIF and TGFβ); an attitude which is an innovative procedure in agent-based modeling structure." (PMID 32384110, 2020). "However, the exact functions of CXCL12 in most cancers are yet to be fully elucidated." (PMID 33363463, 2020).
cancer (continued). "Here, targeting the mTOR pathway may prevent cancer metastasis driven by CXCL12/CXCR4 interaction." (PMID 32483450, 2020). "Furthermore, high concentrations of CXCL12 are present at the common sites of metastases, suggesting that CXCL12/CXCR4 signaling may have a role in the homing of cancer cells to distant organs." (PMID 32224910, 2020). "Further, the selectivity differences seen between our covalently linked conformationally restricted versus non-linked versus hyper-restricted constructs may instruct for the design of dual-specificity inhibitors against both MIF and CXCL12, e.g. for future applications in cancer." (PMID 33239628, 2020). "Moreover, CXCL12 resulted up-regulated during inflammatory processes and cancer." (PMID 32983178, 2020). "Moreover, CXCL12 isoforms could represent new prognostic and predictive biomarkers for several cancers." (PMID 31275385, 2019). "Furthermore, CXCL12 is not secreted in stromal cells of other tissues that are not common sites of metastasis for cancers associated with bone metastasis." (PMID 29642534, 2018). "Thus, targeting the CXCR4/CXCL12 may provide a dual benefit of inhibiting cancer cell migration and lymphangiogenesis to curb lymphatic metastasis." (PMID 29527513, 2018). "In this context, an autocrine regulatory loop between CXCL12 and CXCR4 can be hypothesized also for NETs, since evidence in other cancers suggests that persistent ligand stimulation causes CXCR4 degradation, as well as epigenetic regulation of the entire molecular synapse." (PMID 28186979, 2017). "Furthermore, senescent cells increase the survival of cancer cells via CXCL12/CXCR4 signalling." (PMID 28489070, 2017). "Interestingly, previous studies have demonstrated that, unlike the Caucasian population, the SNP rs1801157 of CXCL12 gene increases cancer susceptibility among Asians." (PMID 28929029, 2017). "Cancer-associated fibroblasts secrete high levels of pro-inflammatory cytokines, including IL-1β, IL-8, IL-10, tumor necrosis factor-alpha (TNFα), monocyte chemoattractant protein-1 (MCP-1/CCL2), SDF-1/CXCL12 and interferon-beta (IFN-β), which have a range of effects on the immune system." (PMID 26828520, 2016). "Finally, our finding that dormant cancer cells express a low level of CXCR4 suggests that treatments targeting the CXCL12-induced CXCR4-mediated signaling may be ineffective for cells at this stage." (PMID 26083776, 2015). "Recent data suggest that different isoforms of CXCL12 may have distinct outcomes for cancer." (PMID 25909600, 2015). "Furthermore, it is unclear whether HSA cells create CXCL12-enriched environments that affect CXCR4-expressing cancer cells, or whether these CXCR4-expressing cells migrate to and/or colonize organs and tissues where there is abundant CXLC12." (PMID 29061949, 2015). "In addition, CXCR4 positive cancer cells can be recruited to CXCL12-rich mesenchymal stroma niches." (PMID 25471741, 2014). "Thus the definition of mechanisms and downstream mediators of CXCR4/R7 activation by CXCL12, in normal and malignant differentiated cells, their progenitors, and in normal and CSCs, is highly relevant for both cancer biology and perspective therapeutic targeting." (PMID 24904289, 2014). "Furthermore, Treg recruitment by CXCL12/CXCR4 in these cancers may potentially be modulated by treatment directed against the HIF-1α pathway." (PMID 21521526, 2011). "The CXCL12/CXCR4 signaling axis has been implicated in both cancer metastases and human immunodeficiency virus type 1 (HIV-1) infection and a more complete understanding of CXCL12/CXCR4 signaling pathways may support efforts to develop therapeutics for these diseases." (PMID 21949786, 2011). "Thus, further studies elucidating the role of CXCL12/CXCR7 axis in cancer development is needed." (PMID 20380740, 2010). "Therefore, CXCL12 signalling may provide a unifying basis for better understanding the complex relationships between cancer and inflammatory cells in terms of receptor crosstalk." (PMID 20946648, 2010).
cancer (continued). "Thus, we have evidence for a specific pathway of activation in mononuclear phagocytes (CXCL12-stimulated Mø release of HB-EGF) that may match the specific biological properties of some cancers (HeLa, DLD-1 and metastatic colon cancer)." (PMID 20946648, 2010). "Strikingly, Dkk3‐null cancer cells led to an increase in myCAF gene expression (ACTA2, CTGF, PDGFRB), with concomitant downregulation of inflammatory CAF markers (CXCL12, CXCL2) in PSCs." (PMID 41147409, 2026). "CXCL12, a chemokine secreted by nerves, mediates the chemoattraction of CXCR4‐positive cancer cells, facilitating their migration toward nerves via a concentration gradient." (PMID 41556039, 2026). "Chemokine CXCL1, also known as Gro-α and MGSA, a ligand of CXCR2, is the best-known CXC chemokine in cancer processes, after CXCL8/IL-8 and CXCL12/SDF-1." (PMID 41898553, 2026). "Carcinoma cells release pro‐fibrotic mediators (TGF‐β, PDGF, FGF) and chemokines (e.g., CXCL12) that recruit local mesenchymal cells and convert them into CAFs." (PMID 41317317, 2026). "Plerixafor prevents key oncogenic processes such as cancer cell mobilization, TME interactions, and immune suppression by blocking CXCR4 binding to CXCL12." (PMID 41383468, 2025). "The CXCL12/CXCR4 signalling axis plays a critical, yet poorly understood, role in the maintenance and expansion of cancer stem cells (CSCs) in TNBC." (PMID 41002447, 2025). "Combining a CXCL12 inhibitor, NOX-A12, with pembrolizumab induced immune response, resulting in SD in heavily pretreated cancer patients." (PMID 39780187, 2025). "CXCL12 and its receptors, CXCR4 and CXCR7, are commonly found in high levels in various cancers, including BLCA." (PMID 40918470, 2025). "Meanwhile, astrocytes engage in bidirectional communication with cancer cells and drive their aggressive growth and metastasis by secreting a variety of cytokines, such as IFNα, TNF-α, CXCL12, TGF-β2, IGFBP2 and CHI3L1." (PMID 41219968, 2025). "Key molecules for cancer progression were inhibited (IL6, IL4, CXCL8, CXCR4, CXCL12; ICAM1, CD44 and BCL2), and pro-apoptotic BAD was activated." (PMID 41595551, 2025). "In fact, several CXCL12—CXCR4 antagonists have been developed, which have shown encouraging results in anti-cancer activity both in in vitro and in vivo studies." (PMID 39859358, 2025). "Specifically, GPR15LG enhances CXCL12-mediated CXCR4 signaling synergistically, promoting wound healing and cell migration across various cell types, including CD4 + T cells and cancer cells." (PMID 40394646, 2025). "CXCL12 exerts its effects primarily through its receptor CXCR4, a G-protein-coupled receptor expressed on various cell types, including cancer cells." (PMID 40481962, 2025). "High CXCL12 expression was observed in ESCC and BC, with mutually exclusive distribution from COL12A1, particularly in ESCC, highlighting these cancers as ideal models for CAFs subtype research." (PMID 41228323, 2025). "Interaction between CXCL12 and CXCR4 leads to the activation of signaling pathways such as PI3K/AKT and MAPK, which promote cancer cell proliferation, survival, and migration." (PMID 40362280, 2025). "The same study reported that CAF-S1 stimulates cancer cell migration and initiates the EMT through CXCL12 and TGF-β pathways." (PMID 40940764, 2025). "In breast cancer, BPA exposure has been linked to the progression of cancer through mechanisms such as the CXCL12/AKT signalling pathway, which promotes epithelial–mesenchymal transition (EMT) and cancer cell migration." (PMID 40647494, 2025). "In this study, the differentiation of NFs into CAFs via co‐culture with cancer cells was confirmed by quantifying the mRNA expression levels of α‐SMA, FAP, FSP‐1, CSPG4, CXCL12, and HGF using qRT‐PCR." (PMID 39801758, 2025). "CXCL12 (alias stromal cell-derived factor 1, SDF-1) is defined as a macrophage chemotactic factor released by adipocytes, stromal cells, and various cancer cells." (PMID 40076892, 2025).
cancer (continued). "The bar charts show the total alteration frequency of six hub genes (CD36, CXCL12, CXCR4, CYBB, ITGAM, PLEK) in pan-cancer." (PMID 40895569, 2025). "It has been shown that TA interferes with several critical pathways involved in cancer development and progression, including NF-κB, PI3K/AKT, ERK1/2, Wnt/β-catenin, JAK/STAT, RAS/RAF/mTOR, TGF-β1/TGF-β1R axis, VEGF/VEGFR signaling and CXCL12/CXCR4 axis." (PMID 41009634, 2025). "This suggests that the upregulation of COL11A1 and the downregulation of CAV1, CXCL12, and SPTBN1 in the cancer microenvironment led to the downregulation of IL-6 and IL-33." (PMID 40898538, 2025). "Ursolic acid (UA), a natural triterpenoid with anti-inflammatory properties, inhibits the secretion of CXCL12 in CAFs, and also reduces the expression of CXCR4 and CXCR7, thereby exerting strong anti-cancer effects." (PMID 40136652, 2025). "The CXCL12/CXCR4 axis facilitates the migration and invasion of cancer cells to distant organs, particularly the liver and lungs, which are common sites of metastasis in CRC patients." (PMID 40426863, 2025). "The mechanism of action of plerixafor primarily revolves around the inhibition of the CXCL12/CXCR4 axis, exerting multiple effects in cancer therapy." (PMID 40909292, 2025). "Functional assays, including wound healing and cell migration assays, were conducted across various cell types, including CD4+ T cells and cancer cells, to evaluate the impact of GPR15LG on CXCL12-mediated CXCR4 signaling." (PMID 40394646, 2025). "This interaction can impact the CXCL12/CXCR4 signaling pathway, which is crucial for cancer cell migration and invasion." (PMID 40426863, 2025). "This review explores how the chemokine receptor type 4 (CXCR4/CXCL12) axis facilitates drug resistance through mechanisms such as epithelial–mesenchymal transition (EMT), cancer stemness, and microenvironmental interactions." (PMID 41002447, 2025). "Conversely, neural structures release factors such as NGF, GDNF, ARTN, and CXCL12 (SDF-1), which act as chemoattractants for cancer cells expressing corresponding receptors." (PMID 40909268, 2025). "Inhibiting CXCL12 action through ulocuplumab results in the inhibition of downstream pro-survival signals (PI3K/AKT, MAPK), reduction in maintenance of cancer stem cells, and increased chemotherapeutic-triggered apoptosis." (PMID 41002447, 2025). "has shown that DPP-4I promotes epithelial-mesenchymal transition through the CXCL12/CXCR4/mTOR axis, thereby inducing cancer progression and metastasis." (PMID 40040724, 2025). "For instance, salivary adenoid cystic carcinoma cells had increased expression of CXCL12 and CXCR4, enhanced invasion, and metastasis after overexpression of NR2F1; knockdown of NR2F1 reduced the invasive phenotype in these cancer cells." (PMID 40955663, 2025). "As the disease progressed, cytokines and chemokines such as GM-CSF, G-CSF, SDF-1/CXCL12, and RANTES/CCR5, regulated by both Wnt/β-catenin and NF-κB signaling pathways, were particularly elevated in high-grade dysplasia and cancer in the murine CAC model." (PMID 40277893, 2025). "Apart from proliferation, CAFs also stimulate cancer cell survival during both chemo- and radiotherapy through exosomally delivered molecules or through direct signaling, for instance via IGF1/2, CXCL12 and β-hydroxybutyrate." (PMID 39696386, 2024). "By activating the CXCL12/CXCR4 axis, cancer stem, and progenitor cells are mobilized to pre-metastatic niches and undergo epithelial-mesenchymal transition (EMT)." (PMID 39070795, 2024). "Beyond the CXCL12/CXCR4 axis’s physiological functions, its dysregulation concerns several pathological conditions, including cancer metastasis, ADs, and human immunodeficiency virus (HIV) infection." (PMID 39070795, 2024).
cancer (continued). "The CXCL12/HMGB1 heterocomplex enhances, via CXCR4, the directional migration and invasiveness of cancer cells characterized by high metastatic potential that possess a fully active thioredoxin system, contributing to maintain red-HMGB1." (PMID 38803493, 2024). "When comparing patients, based on a high or low CXCL12 expression, to survival data, the authors found that a high CXCL12 expression was a prognostic indicator for worse recurrence-free survival (RFS) and cancer-specific survival (CSS)." (PMID 38339310, 2024). "CXCR4 is the receptor for CXCL12, also called stromal cell-derived factor 1 (SDF1), and is the most widely expressed chemokine receptor in human cancer." (PMID 39114657, 2024). "As expected, CXCL12 mediates resistance to CDDP and PTX in EOC cell lines increasing cancer cell proliferation in presence of chemotherapeutic agents." (PMID 39700131, 2024). "The CXCL12/CXCR4 axis, significant in bone metastasis regulation, has inhibitors in clinical trials showing potential to reduce cancer cell proliferation and migration." (PMID 38474093, 2024). "In CXC motif chemokine 12 (CXCL-12)-mediated invasion assays, DARPP-32 overexpression was shown to enhance cancer cell invasion in response to CXCL-12, suggesting that DARPP-32 is actively involved in chemokine-driven metastasis." (PMID 39767693, 2024). "These inhibitory effects would disrupt the cancer cells’ metabolism (by reducing GLUT1) and their invasion and migratory abilities (by reducing MMP7, CXCR4, LOXL2, CXCL12, and vimentin)." (PMID 39272902, 2024). "CAF S1 generated EMT transition and promoted cancer cell migration through TFG-β and CXCL12 pathways." (PMID 39684264, 2024). "Pharmacologically blocking CXCR4 or genetically depleting CXCL12 in LECs enhances CD8+ T cell retention and promotes anti-cancer immunity." (PMID 39211044, 2024). "They found that nano-PIT inhibited the secretion of C-X-C motif chemokine ligand 12 (CXCL12) and ECM deposition regulated by untreated CAFs, mediating T cell exclusion and preventing physical contact between T cells and cancer cells." (PMID 38690275, 2024). "Cancer cells induce TGF-β-dependent stimulation of CXCR4 in monocytes, while CXCL12 expressed by perivascular fibroblasts recruits these migratory TAMs to the blood vessels and entrains the motile cancer cells." (PMID 39003350, 2024). "The interaction between the CXCL12/CXCR4/ACKR3 axis and the STAT3 signaling pathway is crucial in the development and progression of various diseases, including cancer." (PMID 38920657, 2024). "Similarly, CXCL12 produced in lymph nodes may attract CXCR4-expressing cancer cells or leukocytes." (PMID 39195299, 2024). "Tannic acid, a gallotannin found in several natural sources, plays a role in various cancer signaling pathways, including the JAK/STAT, RAS/RAF/mTOR, TGF-β1/TGF-β1R axis, VEGF/VEGFR, and CXCL12/CXCR4 axes." (PMID 39830672, 2024). "As we unravel the intricacies of the immune system and its components, the CXCL12/CXCR4 axis emerges as an essential player, suggesting potential therapeutic targets for several immune-related disorders such as ADs and cancers." (PMID 39070795, 2024). "Its ligand CXCL12 is abundant in organs such as the liver, lymph nodes, and bone, and CXCR4 activation leads to the migration of cancer cells toward these organs, leading to metastasis in these areas." (PMID 39001265, 2024). "The CXCL12/CXCR4 axis plays a role in T cell infiltration and intratumoral trafficking in many cancer types." (PMID 38786066, 2024). "From the perspective of cancer cells, HAT down-regulated the expression of TGF-β, TNF-α, EGF, CCL2, CXCL1, and CXCL12, crucial angiogenic and chemotactic factors for ECs." (PMID 38338342, 2024). "CXCL12 is upregulated in activated pancreatic stellate cells, which can decrease the migration of CD8+T cells to cancer islets in pancreatic ductal adenocarcinoma." (PMID 38644492, 2024).